CSE1L (chromosome segregation 1 like)
Diseases named in the same sentence as CSE1L in open-access papers (continued):
Sharing a sentence is not in itself a finding about the gene and the disease.
cancer (continued). "We amplified the full-length CSE1L cDNA from human cells and cloned it into the pcDNA3.1 eukaryotic-expressing vector to obtain the pcDNA-CSE1L vector to study the effect of increased CSE1L expression on cancer cell proliferation." (PMID 20701792, 2010). "The CSE1L gene is located on chromosome 20q13, a region frequently harbors amplifications that correlate with cancer aggression." (PMID 20701792, 2010). "The results of our study further showed that CSE1L enhanced the invasion and metastasis of B16-F10 cancer cells in animal metastasis studies." (PMID 20701792, 2010). "CSE1L is highly expressed in various cancer types, and its expression level is positively correlated with high tumor stage, high tumor grade, and worse outcomes of cancer patients." (PMID 20701792, 2010). "CSE1L is highly expressed in cancer, and its expression level is well correlated with advanced cancer stage and worse patient outcomes." (PMID 20701792, 2010). "Our results showed that CSE1L regulated cancer cell apoptosis induced by most of the chemotherapeutic drugs that we tested." (PMID 20701792, 2010). "Experimental studies showed that increased CSE1L expression in cancer cells was unable to enhance cancer cell proliferation." (PMID 20701792, 2010). "CSE1L is highly expressed in cancer; thus, if CSE1L plays a role in cancer cell proliferation during cancer development, increased CSE1L expression in cancer cells should be able to increase the proliferation of cancer cells." (PMID 20701792, 2010). "The results of these pathological studies indicated that the expression of CSE1L was positively related to high cancer stage and worse outcomes of cancer patients." (PMID 20701792, 2010). "CSE1L as a secretory protein was assessed by immunoblotting with conditioned medium harvested from B16-F10 cancer cells, and the results showed that CSE1L was present in conditioned medium of serum-starved B16-F10 cells." (PMID 20701792, 2010). "The pathological studies also showed that the expression of CSE1L was positively correlated with a higher cancer stage and higher cancer grade, indicating that CSE1L plays an important role in cancer development and progression." (PMID 20701792, 2010). "However, limited research has focused on the role of CSE1L in the immunotherapy response of OV cancer." (PMID 40406120, 2025). "The CSE1L is an exosome/microvesicle membrane protein with multiple roles in apoptosis, cell survival, chromosome assembly, nucleocytoplasmic transport, microvesicle formation, and cancer metastasis." (PMID 37371576, 2023). "In summary, we analyzed and integrated data from 488 COAD and 155 READ patients, 102 cancer cell lines, more than 15,000 immunostainings, and ∼10,000 raw associations between RBPs and cancer genes to unravel new RBPs involved in COAD (NOP56, NAT10, RBM12, and FKBP1A) and READ (EMG1 and CSE1L)." (PMID 37384253, 2023). "Therefore, further studies are needed to understand the source, association, and secretion of elevated levels of CSE1L from stellate cell sEVs adjacent to a PDAC tumor and the relevant clinical importance in cancer therapy and diagnosis." (PMID 36332889, 2022). "For this reason, abnormal expression of CSE1L may affect genomic stability favoring the cancer progression." (PMID 31383592, 2021). "Nevertheless, CSE1L-high cancers tended to express TAZ at the high level in these cancers." (PMID 34022224, 2021). "AKT/mTOR signaling is involved in CSE1L-mediated cancer growth." (PMID 33854580, 2021). "Thus, we deduce that the miR-451a/CSE1L axis provides novel insights into targeted cancer therapeutics for NPC patients." (PMID 34516344, 2021). "Furthermore, previous studies have revealed that high expression of CSE1L positively correlates with tumor invasion and distant metastasis in different cancers." (PMID 34516344, 2021).
cancer (continued). "CSE1L has been reported to influence apoptosis in several cancers." (PMID 33854580, 2021). "CSE1L is a multifunctional gene that participates in apoptosis, chromosome assembly, nucleocytoplasmic transport, microvesicle formation, chemo-resistance, and cancer progression." (PMID 31139015, 2019). "CSE1L, highly expressed in various cancer types, plays important roles in apoptosis, cell survival, chromosome assembly, nucleocytoplasmic transport, microvesicle formation, and cancer metastasis." (PMID 30144787, 2018). "CSE1L is highly expressed in most cancer types and it is a secretory protein." (PMID 26070816, 2015). "Moreover, CSE1L is known to stimulate the extension of invadopodia and the secretion of matrix metalloproteinases of several cancer cell lines." (PMID 23369209, 2013). "Increased CSE1L expression is unable to enhance the proliferation of cancer cells, thus CSE1L may promote cancer progression by other mechanisms." (PMID 20701792, 2010). "Finally, animal tumor metastasis experiments showed that reduced CSE1L expression decreased the pulmonary metastasis of B16-F10 cells, a highly metastatic cancer cell line, in C57BL/6 mice." (PMID 20701792, 2010). "Various oncogenes may be activated and various anti-oncogenes may be inactivated in tumors; the activated oncogenes and inactivated anti-oncogenes can stimulate the proliferation of cancer cells that highly express CSE1L." (PMID 20701792, 2010). "CSE1L is highly expressed in various cancers especially high stage cancers, and thus it may play important roles in modulating the development and progression of cancer." (PMID 20701792, 2010). "Their results showed that CSE1L mediated apoptosis induced by Pseudomonas exotoxin, diphtheria toxin, and tumor necrosis factor but did not mediate apoptosis induced by ricin, cycloheximide, staurosporine, or etoposide, a cancer chemotherapeutic drug." (PMID 20701792, 2010). "However, it is quite impossible that high expression of CSE1L in cancer cells can enhance chromosome segregation at the mitotic phase of cells and thus increase cancer cell proliferation." (PMID 20701792, 2010). "CSE1L is highly expressed in cancer; therefore enhancing CSE1L expression rather than reducing CSE1L expression in cells is a more appropriate way to study CSE1L-mediated cancer cell apoptosis." (PMID 20701792, 2010). "Therefore, a positive correlation between CSE1L and Ki67 expression in tumors is insufficient to conclude that CSE1L can stimulate cancer cell proliferation." (PMID 20701792, 2010). "CSE1L can associate with microtubules and mitotic spindles, which are cellular organelles for cell mitosis; thus, CSE1L was speculated to play a role in cancer cell proliferation, and was regarded as a proliferation-associated protein in 1996." (PMID 20701792, 2010). "Therefore, it is inappropriate to use the results of CSE1L reduction experiments to assume that CSE1L can stimulate or increase cancer cell proliferation and draw a conclusion that the role of CSE1L in cancer development is to stimulate cancer proliferation." (PMID 20701792, 2010). "Additionally, CSE1L is a novel micro-vesicle membrane protein that may serve as a potential target for the development of efficient antibody-drug conjugates (ADCs) for cancer therapy." (PMID 39430746, 2024). "Besides CSE1L upregulation, other cancers may subvert the acute effects of nuclear ERBB2 directly by mutation." (PMID 37055441, 2023). "Finally, we wanted to know whether and how CSE1L expression correlates with TAZ expression in cancer patients." (PMID 34022224, 2021). "However, they also described a correlation of CSE1L expression with cancer stages." (PMID 30144787, 2018). "Recent studies have proposed that secretory CSE1L might be a potential prognostic marker of cancer." (PMID 23369209, 2013).
cancer (continued). "However, in a study of the distribution of CSE1L in cancer cells, we observed that in addition to granule-like staining in cytoplasm surrounding the perinuclear areas, CSE1L also showed vesicle-like staining in the protrusions of MCF-7 cells in immunofluorescence." (PMID 20701792, 2010). "Therefore, CSE1L may play an important role in mediating the cytotoxicities of chemotherapeutic drugs against cancer cells in cancer chemotherapy." (PMID 20701792, 2010). "Therefore, the CPP32 apoptotic pathway is involved in CSE1L-mediated cancer cell apoptosis." (PMID 20701792, 2010). "Therefore, CSE1L may be a target for developing strategies to improve the efficacy of cancer chemotherapy as well as for screening more potent anticancer reagents." (PMID 20701792, 2010). "Also, CSE1L may be a target for developing strategies to improve the efficacy and outcomes of cancer chemotherapy." (PMID 20701792, 2010). "Therefore, CSE1L is unable to stimulate cancer cell proliferation." (PMID 20701792, 2010). "Therefore, CSE1L may be a useful serological marker for screening, diagnosis and prognosis, assessment of therapeutic responses, and monitoring for recurrence of cancer." (PMID 20701792, 2010). "Alternative splicing was pervasive, with recurrent high-magnitude events at cancer-relevant loci including GJA1 (SE), NF2 (A3/A5), LIN37 (A5), ECT2 (A3/A5), BCL2L11 (A3), UQCRH (A5), CSE1L (A3), BROX (A3), and multiple ZNFs." (PMID 41952686, 2026). "Using two-box analysis of The Cancer Genome Atlas (TCGA) and Genotype-Tissue Expression (GTEx) databases, we compared the expression levels of XPO, including XPO1, CSE1L, XPOT, XPO5, and XPO6, in each tumor and normal tissue." (PMID 39882192, 2025). "PREX1 and CSE1L have been well demonstrated to involve in phosphoinositide AKT signaling pathway and promote cancer progression." (PMID 37749132, 2023). "We observed that TAZ is detected in the nucleus in CSE1L-expressing cancer cells and that WWTR1 silencing antagonizes the effect of CSE1L in cancer cells." (PMID 34022224, 2021). "Our previous study showed that the phosphorylation of CSE1L is regulated by ERK1/2 signaling, an essential signaling downstream of most targets in cancer cells in targeted therapy." (PMID 26070816, 2015). "Therefore, CSE1L may play an important role in cancer progression." (PMID 20701792, 2010). "Matrigel-based invasion assays showed that enhanced CSE1L expression increased cell invasion, and reduced CSE1L expression inhibited the invasion of MCF-7 cancer cells." (PMID 20701792, 2010). "Increased CSE1L expression can enhance both interferon-γ-induced CPP32 expression and the level of the cleaved CPP32 product, thereby inducing apoptosis of HT-29 cancer cells." (PMID 20701792, 2010). "Therefore, CSE1L may regulate the invasion and metastasis of cancer." (PMID 20701792, 2010). "First, pan-cancer analyses were conducted to compare the CSE1L expression between tumor samples and their corresponding normal samples, using the Wilcoxon rank-sum test." (PMID 39430746, 2024). "On the contrary, primary HPaStec sEVs did not modulate the expression of CSE1L or ERK signaling in any of the cancer cells." (PMID 36332889, 2022). "CSE1L expression is correlated with poor overall survival in other cancer types, but to our knowledge, it has not been investigated for PDAC." (PMID 36332889, 2022). "Here, we report that CSE1L was significantly elevated in HPSC sEVs and may contribute towards the cancer signaling pathway in PDAC." (PMID 36332889, 2022).
cancer (continued). "Hence, it is reasoned that CSE1L increases TAZ in the nucleus and induces malignant transformation in cancer cells." (PMID 34022224, 2021). "The mechanism, by which CSE1L confers malignant properties to cancer cells, is not yet fully understood." (PMID 34022224, 2021). "Moreover, we demonstrated that CSE1L increases the nuclear TAZ and enhances malignancy in cancer cells." (PMID 34022224, 2021). "On the other hand, it is likely that TAZ, even when expressed, fails to enhance malignancy in cancer cells lacking CSE1L." (PMID 34022224, 2021). "To this aim, we used human cancer microarray, evaluated CSE1L expression by using a semiquantitative scale of immunoreactive score and examined whether TAZ was detected in the nucleus in human cancers with high levels of CSE1L." (PMID 34022224, 2021). "CSE1L (also named as XPO2) was also found to be 2.209-fold (Roessler liver dataset, P=2.02e-08), 2.218-fold (Roessler liver 2 dataset, P=2.77e-75) and 1.914-fold (Wurmbach liver dataset, P=2.16e-05) increased in HCC cancer tissues." (PMID 31371628, 2019). "Previous studies on cancer cells showed that CSE1L was colocalized with MMP-2 in cytoplasmic areas near the cell membranes and invadopodia, and that CSE1L overexpression enhanced MMP-2 secretion and the invasive ability of cancer cells." (PMID 23369209, 2013). "In this paper, we review the expression of CSE1L in cancer and discuss why CSE1L regulates the invasion and metastasis rather than the proliferation of cancer." (PMID 20701792, 2010). "Increased CSE1L expression enhanced apoptosis induced by doxorubicin, 5-fluorouracil, cisplatin, and 4-OH-tamoxifen, but decreased apoptosis induced by paclitaxel in HT-29 cancer cells and MCF-7 cancer cells." (PMID 20701792, 2010). "Furthermore, as reported in other tumors types, upregulation of DAB2, RND3, TMEM97, CSE1L, MYO1C, and PTPRK have been shown to suppress or functionally redistribute E-cadherin expression in cancer cells, resulting in EMT, increased invasion, advanced tumor stage and poor patient survival." (PMID 27863424, 2016). "Therefore, CSE1L regulates MMP-2 secretion and enhances the invasion of cancer cells." (PMID 20701792, 2010). "However, the results of experimental studies showed that enhanced CSE1L expression is unable to increase proliferation of cancer cells and CSE1L regulates invasion and metastasis but not proliferation of cancer cells." (PMID 20701792, 2010). "Since then many pathological reports demonstrated that the expression of CSE1L in cancer is related to cancer proliferation, although there is no experimental studies to show that increased CSE1L expression in cancer cells can enhance the proliferation of cancer cells." (PMID 20701792, 2010). "Therefore, that report further suggested that although CSE1L definitely plays an important role in cancer progression, it does not stimulate cancer proliferation." (PMID 20701792, 2010). "Nevertheless, our other studies showed that although increased CSE1L expression was unable to induce polarization of MCF-7 cancer cells as it did in HT-29 cells, enhanced CSE1L expression in MCF-7 cells still decreased but not increased the proliferation of MCF-7 cells." (PMID 20701792, 2010). "Nonetheless, the roles of miR-451a and CSE1L have not yet been investigated in NPC, and their interactions have not yet been studied in any human cancers." (PMID 34516344, 2021).
tumor (35 papers, 2009 to 2025). "Intriguingly, we identified two stemness-associated genes, RAD21 and CSE1L, driven by intrinsic tumor variations." (PMID 40406120, 2025). "Among these drivers, RAD21 and CSE1L were found to be tumor intrinsic copy number variation-driven factors associated with tumor stemness and tumor evolution." (PMID 40406120, 2025). "BANCR causes doxorubicin resistance by modulating the miRNA-203/chromosome segregation 1 like (CSE1L) complex in tumor cells." (PMID 36362222, 2022). "In this study, we firstly demonstrated that BANCR and CSE1L expressions were both up-regulated in CRC tumor tissues, and CSE1L expression was positively associated with BANCR expression and clinicopathological factors of CRC." (PMID 30144787, 2018). "The findings showed that high CSE1L cytoplasmic expression was associated with the depth of tumor penetration and disease stage." (PMID 23369209, 2013). "Furthermore, additional experimental verification is imperative to unveil the molecular mechanisms underlying the relationship between CSE1L, immunotherapy response, and tumor advancement." (PMID 40406120, 2025). "Moreover, CSE1L expression was positively associated with BANCR expression in 32 cases of CRC tumor tissues." (PMID 30144787, 2018). "Result showed that CSE1L expression was associated with depth of tumor (p<0.05)." (PMID 30144787, 2018). "Cytoplasmic CSE1L is associated with microtubules; this association has been shown to stimulate the extension of invadopodia (invasive feet) and to enhance the migration of tumor cells." (PMID 23369209, 2013). "As mentioned, cytoplasmic CSE1L is associated with the development of microtubules, and this association may stimulate invadopodia extension and may enhance the migration of tumor cells." (PMID 23369209, 2013). "Molecular mechanism study found that STARD14 may promote tumor progression via directly act on CSE1L, and associated with several multiple tumor-related signaling, including Wnt/ β - catenin signaling, PI3K / Akt signaling, Cdc42 signaling, and SAPK / JNK signaling." (PMID 37790851, 2023). "Moreover, CSE1L level was positively associated with BANCR level in CRC tumor tissues." (PMID 30144787, 2018). "As the tumor continues to evolve, the expression of CSE1L decreases, resulting in a reduction in tumor cell stemness." (PMID 40406120, 2025). "Then, to validate this founding, we stratified malignant tumor cells based on the expression of CSE1L into CSE1L+ malignant cells and CSE1L- malignant cells." (PMID 40406120, 2025). "This enabled us to identify the core genes associated with tumor stemness induced by tumor intrinsic variations and finally we selected four genes: RAD21, EXOSC4, CSE1L and RAE1." (PMID 40406120, 2025). "Intriguingly, we observed that the expression of CSE1L increased with the progression of tumor malignancy." (PMID 40406120, 2025). "CSE1L promotes tumor progression by enhancing cell proliferation and contributing to drug resistance." (PMID 39430746, 2024). "As a key factor in the nuclear transport pathway, CSE1L participates in nucleocytoplasmic transport, a crucial process in tumor growth and development." (PMID 39430746, 2024). "CSE1L overexpression triggered microvesicle generation and tumor progression, thereby regulating the Ras-ERK signaling pathway." (PMID 36332889, 2022). "Collectively, our present data substantiate that miR-451a exerts tumor-suppressive functions by targeting CSE1L to hinder cell proliferation, migration, and invasion in NPC." (PMID 34516344, 2021). "In this study, CSE1L was identified as a novel downstream target of FLVCR1 and implicated in the regulation of tumor growth and migration in ESCC." (PMID 33842377, 2021).